MMP9 (matrix metallopeptidase 9)
Diseases named in the same sentence as MMP9 in open-access papers (continued):
Sharing a sentence is not in itself a finding about the gene and the disease.
cardiac hypertrophy (49 papers, 2011 to 2025). "MMP2-deficient mice showed reduced myocardial hypertrophy and fibrosis, while MMP9 deficiency partially improved myocardial hypertrophy and fibrosis following pressure overload." (PMID 22943504, 2012). "Angiotensin II has been implicated in the up-regulation of the MMP-9 and it has been showed that the former is associated with the cardiac hypertrophy process and cardiac remodeling." (PMID 22204652, 2011). "Furthermore, by searching the database, we can easily find that, in the pressure overload model of heart disease, MMP2-deficient mice showed reduced myocardial hypertrophy and fibrosis while MMP9 deficiency partially improved myocardial hypertrophy and fibrosis following pressure overload." (PMID 32982761, 2020). "Many studies have shown that MMPs, particularly MMP-2 and MMP-9, are involved in cardiac remodeling processes, such as cardiac hypertrophy and fibrosis." (PMID 40943161, 2025). "In our previous study, we found that increased SIRT3 expression in the myocardium of a porcine model of pathological myocardial hypertrophy effectively inhibited the expression of MMP2 and MMP9, limiting the progression of pathological myocardial hypertrophy." (PMID 40893347, 2025). "Conversely, UBE3A knockdown by siRNAs exacerbated isoproterenol-induced cardiac hypertrophy by activating the TLR4/MMP-9 pathway." (PMID 38515760, 2024). "Conversely, overexpression of MMP9 in macrophages exacerbates inflammation, ventricular hypertrophy, and cardiac fibrosis in aged mice." (PMID 38270118, 2023). "More importantly, our results suggested that rapamycin alleviated the dysregulation of MMP-9/TIMP-1 balance while improving Testosterone-induced OVX SHR cardiac hypertrophy." (PMID 34874016, 2022). "The mechanism by which TLR4 influences myocardial hypertrophy mainly involves the MyD88-dependent pathway and MMP9-dependent pathway." (PMID 35046797, 2021). "In hypertensive SHR rats which developed cardiac hypertrophy, we also observed downregulation of MMP-9 mRNA while MMP-2 mRNA was preserved." (PMID 33400052, 2021). "Supportively, our results demonstrated the high expression of MyD88, NF-κB, and MMP9 in mice with myocardial hypertrophy." (PMID 35046797, 2021). "Catechins also significantly reduced heart hypertrophy, plasma glucose levels, and matrix metallopeptidase 9 (MMP-9) levels." (PMID 34867384, 2021). "Coincidently, macrophage-specific over-expression of MMP9 significantly exacerbates cardiac hypertrophy in mice." (PMID 33898415, 2021). "Specific MMP9/2 inhibition by the SDS3 antibody attenuates cardiac hypertrophy, cardiomyocyte remodeling, leucocyte infiltration and mitochondrial damage." (PMID 32271823, 2020). "Therefore, in the present study, MMP9 and sST2, promising biomarkers for cardiac fibrosis and hypertrophy, and CRP, a conventional biomarker for inflammation, were measured in addition to echocardiography." (PMID 39264503, 2025). "Further supporting this, the observed reduction in HFD-induced fibrotic gene expression (Col1a1, Col3a1, Mmp9) by SAAR suggests a protective effect against the abnormal remodeling of the extracellular matrix that normally accompanies pathological cardiac hypertrophy." (PMID 39770968, 2024). "UBE3A is vital for alleviating cardiac hypertrophy via the UBE3A/TLR4/MMP-9 pathway." (PMID 38515760, 2024). "Additionally, the level of matrix metallopeptidase 9 (MMP9), which is involved in cardiac hypertrophy and fibrosis, is enriched." (PMID 38270118, 2023). "Furthermore, macrophage-specific overexpression of MMP-9 in transgenic mice enhanced cardiac hypertrophy." (PMID 33400052, 2021). "Therefore, the present study was designed to investigate the role of GPR30, and its downstream signaling pathway focusing on MMP-9–mediated fibrosis in transverse aortic constriction (TAC)–induced cardiac hypertrophy of aged female mice." (PMID 34803680, 2021).
cardiac hypertrophy (continued). "In our meta-analysis, we demonstrate that collagens, matrix metalloproteinases MMP2 and MMP9, immune system markers and markers in the TGFß signaling, and cardiac hypertrophy pathway are upregulated in anthracycline-induced cardiomyopathy whereas the AKT pro-survival pathway is downregulated." (PMID 34052857, 2021). "Additionally, the levels of the molecular markers of cardiac hypertrophy, fibrosis, and apoptosis (such as MyHC, Col-1, MMP-9, TGF-β, Bax, Bcl-2, and Caspase-3) were decreased by PD98059 or LY317615." (PMID 34395424, 2021). "Indeed, MMP-9 is involved in the intracellular cleavage of myosin filaments, a mechanism that leads to ventricular hypertrophy." (PMID 31963569, 2020). "The MMP-9 protein level was increased in ISO-induced cardiac hypertrophy rat model." (PMID 28570599, 2017). "We found that CA ameliorated cardiac inflammation and myocardial hypertrophy after RH by regulating the expressions of IL-17, TNF α, MMP9, and COX2 in both the IL-17 and TNF signaling pathways." (PMID 39337549, 2024). "In the present study, the high expression of MMP-9 and the low expression of TIMP-1 displayed imbalance in the Testosterone-induced cardiac hypertrophy of OVX SHR." (PMID 34874016, 2022). "It has been demonstrated that captopril improved ventricular hypertrophy in rats by suppressing MMP-2 and MMP-9 expression." (PMID 30347737, 2018). "In agreement with this concept, SalA, as a novel MMP-9 inhibitor, ameliorates cardiac fibrosis and hypertrophy in SHR, indicating MMP-9 inhibitor is promising in the treatment of hypertensive fibrosis." (PMID 23533637, 2013). "Hypertensive patients with cardiac hypertrophy have been reported to have reduced plasma levels of MMP1, MMP2 and MMP9, while elevated plasma TIMP1 levels have been reported in hypertensive patients that correlated with diastolic dysfunction and LV fibrosis." (PMID 22943504, 2012). "Heart tissues of SHRs exhibited increased mRNA expression of ANP, BNP and β-MHC and protein expression of myocardial hypertrophy markers, including Collagen I, Collagen III, matrix metalloproteinase 2 (MMP 2) and matrix metalloproteinase 9 (MMP 9), compared with the age-matched WKY rats (p < 0.05)." (PMID 38715976, 2024). "Hemodynamic measures from MMP9 knockout mice (MMP9 KO) indicated they had attenuated PH parameters compared to WT mice based on an ECHO assessment of pulmonary artery pressure, right ventricular systolic pressure, and Fulton index hypertrophy measurements." (PMID 38001814, 2023). "Furthermore, by using meta-regression, we show temporal changes in markers for TGFß-induced fibroblast activation (CTGF protein), cardiac hypertrophy/wall stress (BNP protein), and MMP9." (PMID 34052857, 2021). "The mRNA levels of myocardial hypertrophy marker genes, including atrial natriuretic factor (ANF), matrix metalloproteinase (MMP)-9 and MMP-13, were detected by qRT-PCR, and the expressions of apoptosis-related proteins (Bcl-2 and Bax) were measured by western blotting." (PMID 28513772, 2017). "In addition, hypertrophic markers such as ANP and BNP, and the cardiac fibrotic marker MMP9 were also substantially increased in TAC-challenged hypertrophic hearts compared with sham group, suggesting that TAC-induced myocardial hypertrophy model was successfully constructed." (PMID 37219631, 2023). "However, the role of ERK1/2-mediated MMP-9 signaling in the protection of GPR30 against cardiac hypertrophy in aged female mice has not been investigated." (PMID 34803680, 2021). "Contrarily, AT-001 treatment did not influence the myocardial expression of MMP9 and MMP7, both of which are potent regulators of cardiac fibrosis and hypertrophy." (PMID 36978133, 2023). "Foxm1 deletion did not alter mRNA expression of genes critical for cardiac hypertrophy and fibrosis such as α-SMA, collagen 1α1, CaMKIIδ, TNFα, BMP4, MMP9, CXCR4 and Hey2." (PMID 23144938, 2012).
endometrial cancer (47 papers, 2009 to 2026). Primary or metastatic malignant neoplasm involving the endometrium (mucous membrane that lines the endometrial cavity). "Similar associations were observed for MMP-9, as it was found to correlate with the histological grade and the disease stage of endometrial carcinoma." (PMID 34830354, 2021). "Our study was the first one to assess the total serum levels of NGAL and MMP-9 using the logistic regression model which facilitates attempted estimation of the preoperative risk of endometrial cancer." (PMID 29089666, 2017). "Moreover, the clinical relevance of the NGAL (neutrophil gelatinase-associated lipocalin)/MMP-9 pathway was investigated in patients with endometrial cancer." (PMID 33287452, 2020). "MMP-2 and MMP-9 have been found to be associated with invasive endometrial cancers." (PMID 29391048, 2018). "For diagnostic biomarker panels, MMP9 and PKM were reliable for discriminating endometrial cancer, while the combination of CTNB1, XPO2, and CAPG revealed higher performance in distinguishing endometrioid from serous endometrial cancer types." (PMID 39194522, 2024). "Endometrial cancer progression has also been associated with increased expression of MMP-2 and MMP-9." (PMID 36982551, 2023). "MMP9 is a MMP that is key to the progression of endometrial cancer, degrading extracellular matrix and leading to the possible extravasation of malignant cells into the bloodstream or lymphatics to enable metastatic spread." (PMID 34313032, 2022). "Several studies have found that MMP-9, one of the extracellular matrix-degrading proteinases, was involved in EC’s (endometrial cancer) clinical progression and prognosis." (PMID 36387161, 2022). "ALKBH5 promoted the activity of endometrial cell via upregulation of COL1A1 and MMP9 expression, which finally promoted the progression of endometrial cancer." (PMID 32913456, 2020). "The analysis of NGAL/MMP-9 indicator in patients with endometrial cancer as compared to patients with benign endometrium changes was statistically significant differences between the compared groups—64.7 pg/mL/44.4 pg/mL (p = 0.001)." (PMID 29089666, 2017). "MMP-9 is a protein that plays an apparently crucial role in the proliferation of cells in endometrial cancer." (PMID 29089666, 2017). "In the comparison of mean protein levels between the patients with endometrial cancer and the patients with endometrial myomas, the statistical significance of differences was stronger for MMP-9 as compared to NGAL (p = 0.0002/p = 0.005)." (PMID 29089666, 2017). "The AUC value for NGAL/MMP-9 indicator which compared the patients with endometrial cancer to patients with benign endometrial changes was 0.92." (PMID 29089666, 2017). "Differences were also observed in MMP-9 levels between the patients with endometrial cancer and patients with normal endometrium (p = 0.001) or endometrial polyps (p = 0.003)." (PMID 29089666, 2017). "SDC1 has also been demonstrated to be enhance endometrial cancer invasion by modulating matrix metalloproteinase-9 (MMP-9) expression through nuclear factor kappaB (NF-κb)." (PMID 29340066, 2017). "The transfection of the emmprin siRNA caused significant decreases in the expression of VEGF, MMP-2 and MMP-9 in endometrial cancer cells." (PMID 22640183, 2012). "MMP-1 and -7 were expressed in all but chorioncarcinoma cells, whereas MMP-9 and -15 showed the same expression pattern concerning endometrial cancer cell lines." (PMID 20942921, 2010). "In this study, DOCK1 could promote the migration and invasion of endometrial cancer cells through decreasing E-cadherin expression and upregulating MMP9 and Ezrin expressions." (PMID 38438882, 2024). "Serum LCN2 and MMP9 levels may be good clinical tools for the auxiliary diagnosis of early-stage endometrial cancer." (PMID 39973816, 2024). "MMP-9 appears to play important roles in various cancer types, including endometrial cancer." (PMID 36945954, 2023).
endometrial cancer (continued). "A significantly higher percentage of slides showed high immunoreactivity with MMP-9 in grade 2 (28.6%), grade 3 (33.3%), endometrial serous (57.1%), and undifferentiated endometrial carcinomas (100%) when compared to the proliferative endometrium (0%) (p < 0.05)." (PMID 36945954, 2023). "Silencing of TICRR and PPIF led to enhance the expression of epithelial marker E-cadherin and decrease the mesenchymal marker N-cadherin and metastasis associated genes MMP9 as well as proliferation-related marker CCND1, suggesting their involvement in the progression of endometrial cancer." (PMID 33495413, 2021). "Also, the MMP-9 and MT1-MMP expression in endometrial carcinoma tissue was demonstrated to be significantly associated with the presence of myometrial invasion and vascular/lymphatic invasion." (PMID 34830354, 2021). "VEGFB, MMP9, and neutrophils may cooperatively regulate angiogenesis in the primary metastasis of endometrial carcinoma." (PMID 33363026, 2020). "Multifactorial logistic regression analysis in the final method revealed that NGAL and MMP-9 variables were independent of the endometrial cancer risk." (PMID 29089666, 2017). "Reports of higher expression of MMP-9 in endometrial cancer patients were also published." (PMID 29089666, 2017). "MMP-9 appears to play a crucial role in the formation of metastases of endometrial cancer." (PMID 29089666, 2017). "In the present study, the finding that EZH2 was associated with deep myometrial invasion supports the hypothesis that EZH2 may be an important factor in the invasion of endometrial cancer cells by regulating E-cadherin, β-catenin and MMP9." (PMID 25295088, 2014). "Overall, the inhibition caused by the emmprin siRNA affected cell proliferation, migration and invasion through TGF-β, EGF, NF-κB, VEGF, MMP-2 and MMP-9 expression, which in turn resulted in increased levels of E-cadherin and reduced levels of Vimentin and Snail in endometrial cancer." (PMID 22640183, 2012). "In this study, we used RT-PCR assays to examine whether VEGF, MMP-2 and MMP-9 were affected in endometrial cancer cells after transfection of the emmprin siRNA." (PMID 22640183, 2012). "Emmprin knockdown by the siRNA led to cell proliferation, migration and invasion through TGF-β, EGF, NF-κB, VEGF, MMP-2, and MMP-9 expression, which in turn resulted in increased levels of E-cadherin and reduced levels of Vimentin and Snail in endometrial cancer." (PMID 22640183, 2012). "Previous studies have shown increased expression of MMP-2 and MMP-9 in pre- and postmenopausal patients with polyps, suggesting that their expression could depend on the hormonal status of patients with endometrial polyps and type I endometrial cancer." (PMID 36982551, 2023). "Among 52 proteins previously identified by the research team, 8 proteins (MMP9, KPYM, LDHA, CADH1, NAMPT, MPO, ENOA and CAPG) achieved the highest accuracy in diagnosing endometrial cancer in CVF." (PMID 39194522, 2024). "This study identified 28 differentially expressed proteins in endometrial cancer samples, with LDHA, PKM, MMP9, NAMPT, and SPIT1 showing the best performance in distinguishing endometrial cancer from normal tissues." (PMID 39194522, 2024). "A four-marker panel comprising CSTA, S100A7, MMP9 and SERPINA10 predicted endometrial cancer with an AUC of 0.84 (0.77–0.92), sensitivity of 72.2%, specificity of 87.8%, NPV of 86.7% and PPV of 74.1%." (PMID 36807337, 2023). "Previous study has shown that SOE inhibited dose-dependently the expression of MMP-9, MMP-2 and u-PA in endometrial cancer RL95-2 cells, thereby inhibiting migration and invasion." (PMID 35890125, 2022). "He found that STMN1 promotes the growth and invasion of endometrial carcinoma by mediating the secretion and activation of MMP2 and MMP9 proteins." (PMID 35126478, 2022).
endometrial cancer (continued). "Several reports have demonstrated that MPA can alter MMP-9 levels, where levels are increased in macrophages and, alternatively, reduced in BV2 microglial, endometrial cancer, and primary amnion epithelial cells." (PMID 32317959, 2020). "In this study, the overexpression of miR-302a-5p/367-3p or knockdown of HMGA2 in endometrial cancer cells decreased the expression of EMT-related proteins, such as MMP-2, MMP-9, Snail, Slug and N-cadherin, while increasing the expression of E-cadherin." (PMID 29391048, 2018). "The results indicated that RUNX1 promotes distant metastasis in endometrial carcinoma at least partially dependent on the regulation of MMP-2 and MMP-9 expression." (PMID 29391048, 2018). "In our study, we were able to demonstrate that patients with endometrial cancer presented with NGAL and MMP-9 levels higher than those with healthy endometrium or benign endometrial lesions." (PMID 29089666, 2017). "The serum levels of HA and the SHAP-HA complex had a significant correlation with the MMP-9, and TIMP-1 in endometrial cancer patients." (PMID 21904555, 2011). "Former studies showed an involvement of Sdc-1 in MMP-9 regulation, a main target of TIMP-1, mediating endometrial cancer invasion." (PMID 21044331, 2010). "Echinacoside was found previously to reduce the expression of MMP9 in endometrial cancer, however, no previous study illustrates the ability of echinacoside to reduce the expression of MMP9 in HCC." (PMID 38461536, 2024). "We noted that the expression of MMP-9 did not vary between the various histologic subtypes of endometrial cancer studied." (PMID 36945954, 2023). "In endometrial cancer, CAFs activated PI3K/AKT and MAPK/ERK signals in a paracrine-dependent manner, or increased MMP-2 and MMP-9 secretion in an autocrine-dependent manner through CXCL12-CXCR4 axis, thus promoting the invasion and metastasis of endometrial cancer." (PMID 37497001, 2023). "To further explore the mechanism underlying the effect of TMEFF1 on the invasion and migration of endometrial carcinoma cells, we used western blot to determine the changes in the key EMT proteins E-cadherin, Vimentin, MMP2, and MMP9 between before and after TMEFF1 knockdown." (PMID 34475991, 2021). "The SHAP-HA complex may promote the lymph-vascular space involvement and the synthesis and activation of MMP-9 and TIMP-1 in the progression of endometrial cancer." (PMID 21904555, 2011). "The present study has also demonstrated that the serum levels of MMP-9 and TIMP-1 were significantly higher in the endometrial cancer group than in the healthy control group, and serum MMP-9 was elevated according to the depth of myometrial invasion and lymph-vascular space involvement." (PMID 21904555, 2011). "Besides, AZD1080 exposure decreased NF-kB, Cyclin D1 and MMP9 expression while increased P21 expression, thus we guess that AZD1080 may be an effective drug for treating endometrial carcinoma." (PMID 27050373, 2016). "Decreased expression of pro-MMP-9, pro-MMP-2 and MMP-2 in endometrial cancer cell lines after in vitro administration of medroxy progesterone acetate, an synthetic progesterone preparation, suggests that ECM remodelling could well be controlled by P4 as well as by LH in the CL tissue." (PMID 21291521, 2011). "Because the levels of the SHAP-HA complex showed a significant positive correlation with the levels of MMP-9 and TIMP-1, the SHAP-HA complex may promote the lymph-vascular space involvement and the synthesis and activation of MMP-9 and TIMP-1 in the progression of endometrial cancer." (PMID 21904555, 2011). "Moreover, we have shown in our laboratory that TGF-β isoforms efficiently inhibit cellular proliferation in human endometrial carcinoma cell lines and that TGF-β3 increases invasiveness of endometrial carcinoma cells through PI 3-K upregulation of XIAP and protein kinase C induction of MMP-9." (PMID 19656380, 2009).